FCRL1 (Fc receptor like 1)
Description:
Type I transmembrane surface glycoprotein preferentially expressed by B-cells that regulates BCR-mediated signaling responses. Recruits ABL1 as the intracellular effector molecule to enhance B-cell activation (By similarity). Also plays a negative role by suppressing ERK activation under homeostatic and BCR-stimulated conditions in a GRB2-dependent manner (By similarity).
Synonyms: FcRH1; CD307a; IFGP1; IRTA5
Tractability: Antibody: UniProt places it where antibodies can reach, with high confidence; UniProt predicts a signal peptide or a membrane-spanning region; its Gene Ontology location is reachable by antibodies, with medium confidence. PROTAC: its protein half-life has been measured.
Gene: Protein-coding gene on chromosome 1 (157,792,249 to 157,820,183, reverse strand). Ensembl gene ENSG00000163534.
Subcellular location: Cell membrane
Gene Ontology:
Molecular function: coreceptor activity; transmembrane signaling receptor activity
Biological process: B cell activation; cell surface receptor signaling pathway; immune response
Cellular component: cell surface; external side of plasma membrane; plasma membrane
Genetic constraint (gnomAD): Loss-of-function variants: 29 observed, 48.62 expected, observed/expected ratio (o/e) 0.6, 90% interval 0.44 to 0.81. The upper end of that interval is the gene's LOEUF score, 0.81, which puts it in group 3 of 6, group 1 being the genes least tolerant of losing a copy. Missense variants: 511 observed, 538.95 expected, observed/expected ratio (o/e) 0.95, 90% interval 0.88 to 1.02. Synonymous variants: 212 observed, 210.07 expected, observed/expected ratio (o/e) 1.01, 90% interval 0.9 to 1.13.
Homologues: Orthologues: macaque FCRL1 (88% identical), guinea pig FCRL1 (65% identical), dog FCRL1 (63% identical), rat Fcrl1 (48% identical), mouse Fcrl1 (47% identical). Paralogues in human: FCRL2 (54% identical), FCRL3 (52% identical), FCRL5 (48% identical), FCRL4 (33% identical), FCRL6 (25% identical), PECAM1 (21% identical), FCGR1A (12% identical), FCRLA (12% identical), FCRLB (11% identical), MILR1 (8% identical), FCGR2B (7% identical), C17orf99 (6% identical), and 5 more.
Diseases named in the same sentence as FCRL1 in open-access papers:
FCRL1 is named in the same sentence as 46 diseases in open-access papers, as found by Europe PMC text mining. Sharing a sentence is not in itself a finding about the gene and the disease. The quoted sentences say what the papers report.
melanoma (5 papers, 2013 to 2022). A malignant, usually aggressive tumor composed of atypical, neoplastic melanocytes. "Examples of such genes are: RNASET2, a known tumor antagonist in melanoma; and FCRL1, encoding a glycoprotein linked to the disease’s progression." (PMID 33704427, 2021). "It is noteworthy that two proteins namely MAGEC1 (Melanoma antigen family c1) and FCRL1 (Fc receptor-like 1), which were known for melanoma progression were up-regulated in metastatic melanoma." (PMID 28302167, 2017). "Randall S. Davis identified that FCRL1 overexpressed in breast, melanoma, and lung cancer may be a potential biomarker and therapeutic target." (PMID 36246400, 2022).
diffuse large B-cell lymphoma (4 papers, 2023 to 2025). "Therefore, the current study aimed to determine the diagnostic and prognostic functions of FCRL1 and BAFF in Egyptian patients with diffuse large B-cell lymphoma (DLBCL), the most prevalent subtype of B-cell non-Hodgkin lymphoma." (PMID 39941037, 2025). "Notably, FCRL1 is overexpressed in subsets of naive and memory B-cells, as well as in malignant B-cells, including those in diffuse large B-cell lymphoma (DLBCL), an aggressive and often treatment-resistant hematological malignancy." (PMID 41836520, 2025). "However, in diffuse large B-cell lymphoma (DLBC), FCRL1-5 and A gene expression did not exhibit significant correlations with markers of other TILs, except for B cells, which demonstrated a strong positive correlation." (PMID 37285836, 2023).
hairy cell leukemia (4 papers, 2016 to 2025). Hairy cell leukemia (HCL) is a rare type of leukemia in which abnormal B-lymphocytes are present in the bone marrow, spleen and peripheral blood. "It is broadly expressed by mature B-cells, and has also been found on a majority of chronic lymphocytic leukemia (CLL), follicular lymphoma (FL), hairy cell leukemia (HCL), and mantle cell lymphoma (MCL) cells; therefore, FCRL1 may be a potential target for immunotherapy of B-cell disorders." (PMID 27446638, 2016).
autoimmune disorders (3 papers, 2016 to 2025). "In a previous study, two other autoimmune disorders, HT and GD, showed a significant decrease in the FCRL1 gene expression level but a considerable increase in FCRL2 and FCRL4 genes expression with compare to the corresponding healthy controls." (PMID 34466580, 2020). "While the role of FCRLs in the pathogenesis of autoimmune diseases remains unclear, a recent study reported downregulation of FCRL1 and upregulation of FCRL2 transcripts in Hashimoto's thyroiditis (HT) and Graves' disease (GD)." (PMID 27446638, 2016). "A comparative analysis of FCRL1 gene expression showed that the expression level of FCRL1 in PBMCs is significantly higher in patients with autoimmune diseases like multiple sclerosis, lupus anticoagulans, Takayasu's arteritis and also in von Willebrand disease as compared with the healthy controls." (PMID 27446638, 2016). "Understanding the complex signaling pathways mediated by FcRL1 and other FcRL family members could provide valuable insights into the formulation of targeted treatments for autoimmune disorders, B-cell malignancies, or other diseases involving aberrant B-cell activation." (PMID 40650084, 2025). "Further research into the precise molecular mechanisms by which FcRL1 influences BCR signaling and the potential implications of FcRL1 dysfunction in autoimmune disorders and B-cell malignancies may pave the way for developing targeted therapies that modulate B-cell responses in disease states." (PMID 40650084, 2025).
lymphoma (3 papers, 2016 to 2025). A malignant (clonal) proliferation of B- lymphocytes or T- lymphocytes which involves the lymph nodes, bone marrow and/or extranodal sites. "These new insights into the molecular underpinnings of DBCL biology suggest that targeting the FCRL1/BAFF axis may represent a novel therapeutic strategy of personalized approaches to lymphoma treatment, particularly for high-risk patients who exhibit poor responses to conventional R-CHOP therapy." (PMID 39941037, 2025). "Progress in understanding its regulatory properties, along with evidence for its over-expression by mature B cell leukemias and lymphomas, collectively imply important yet unmet opportunities for FCRL1 in B cell development and transformation." (PMID 37822931, 2023). "Although confirmation at the protein level in well-annotated primary samples is required, these data merit further dissection of FCRL1 as biomarker in the pathogenesis and treatment of aggressive lymphomas." (PMID 37822931, 2023). "Considering that FCRL1 and FCRLA are both associated with lymphoma, these secreted forms could potentially serve as targets for immunotherapy." (PMID 27446638, 2016). "Even though it is overexpressed by many different leukemias and lymphomas, there is little evidence for FCRL1 as a high-frequency target of recurrent mutation or genetic alteration in the catalogue of somatic mutations in cancer (COSMIC) database or other genomic analyses of lymphomas." (PMID 37822931, 2023). "While our study provides valuable insights into the prognostic significance of FCRL1 and BAFF expression in lymphoma patients, several limitations warrant consideration." (PMID 39941037, 2025). "This study showed that FCRL1 and BAFF mRNA expression levels were significantly higher in lymphoma patients than in controls." (PMID 39941037, 2025). "Interestingly, a query of samples from this study revealed significantly higher FCRL1 transcripts in MHG samples followed by GCB-DLBCL, ABC-DLBCL, and unclassified lymphoma samples." (PMID 37822931, 2023).
mantle cell lymphoma (3 papers, 2016 to 2025). Mantle cell lymphoma is a rare form of malignant non-Hodgkin lymphoma affecting B lymphocytes in the lymph nodes in a region called the ``mantle zone''. "Unusual expression of FCRL1 and BAFF was stated in diffuse large B cell lymphoma (DLBCL) cell lines and Burkitt lymphoma (BL) as well as follicular lymphoma (FL), mantle cell lymphoma (MCL), chronic lymphocytic leukemia (CLL), hairy cell lymphoma (HCL), and multiple myeloma (MM)." (PMID 39941037, 2025).
acute lymphoblastic leukemia (2 papers, 2023 to 2025). Leukemia with an acute onset, characterized by the presence of lymphoblasts in the bone marrow and the peripheral blood. "However, consistent with its distribution pattern during normal B cell development, FCRL1 expression appears to be lower in cases of acute lymphoblastic leukemia (ALL), which derives from bone marrow B cell precursors, and multiple myeloma that originates from transformed plasma cells." (PMID 37822931, 2023). "However, FCRL1 expression is lower in acute lymphoblastic leukemia (ALL) and multiple myeloma, regardless of its distribution during normal B cell development." (PMID 39941037, 2025).
B-cell lymphoma (2 papers, 2025). "Top proteins that were consistently associated with B-cell lymphoma across the EPIC, ARIC and UK Biobank cohorts included: CXCL13, sCD23, FCRL1, FCRL3, SEMA7A, CD72, CD48, LY9 and VCAM1." (PMID 40894013, 2025). "Many advancements to identify FCRL1 regulatory characteristics and the evidence of its over-expression in B cell lymphoma reflect essential functions of FCRL1 in B cell development." (PMID 39941037, 2025). "Strikingly, all the top proteins associated with B-cell lymphoma development (sCD23, FCMR, FCRL1, FCRL3, SELL, SEMA7A and SEMA4A) were most strongly associated with CLL development, suggesting CLL was a major driver of the top protein associations observed in the grouped analysis." (PMID 40894013, 2025).
Burkitt lymphoma (2 papers, 2025). A rare form of malignant mature B-cell non-Hodgkin lymphoma. "Previous work on the interaction of human FcRL1 (hFcRL1) on the calcium signaling in FcRL1-positive Burkitt’s lymphoma (BL) cells provided additional context for the mechanistic understanding of the role of this receptor in B-cell activation." (PMID 40650084, 2025).
leukemia (2 papers, 2013 to 2023). A malignant (clonal) hematologic disorder, involving hematopoietic stem cells and characterized by the presence of primitive or atypical myeloid or lymphoid cells in the bone marrow and the blood. "Initial studies detected FCRL1 expression in human leukemia and NHL cell lines, including BLs." (PMID 37822931, 2023).
multiple sclerosis (2 papers, 2016 to 2020). A progressive autoimmune disorder affecting the central nervous system resulting in demyelination. "In some studies, it has been demonstrated that the FCRL1 gene expression levels expression in patients with multiple sclerosis, lupus anticoagulants, arteritis, and von Willebrand disease are higher than that of healthy subjects." (PMID 34466580, 2020).
COVID-19 (1 paper, 2021). A disease caused by infection with severe acute respiratory syndrome coronavirus 2. "This bias was not homogeneous across all Treg-up signature genes, a ranked plot of differential expression in each donor revealing a small subset of TregUp signature genes actually down-regulated in severe COVID-19 patients (including TLR5, ID3, and FCRL1)." (PMID 34433692, 2021).
immunodeficient diseases (1 paper, 2022). "The functional capacities of the highly expressed DEGs in the Chinese Simmental cattle mainly focused on inflammatory diseases (CXCL9 and FCRL1), immunodeficient diseases (ADM2, CCL5, and CAMKV), carcinoma (CXCL11, JAKMIP2, GZM, and DNAAF1), and GTP binding and GTPase activity (NUGGC)." (PMID 35495650, 2022).
lung fibrosis (1 paper, 2022). "Similarly, Flt3L and FCRL1 have been implicated in the regulation of immune cell development and activation and lung fibrosis." (PMID 35967328, 2022).
macrosomia (1 paper, 2023). "The roles of FCRL1 and RNASE3 in inflammatory pathways point to an important role of the immune system in metabolic pathology in GDM related macrosomia." (PMID 36788507, 2023).
sarcoidosis (1 paper, 2019). Sarcoidosis is a multisystemic disorder of unknown cause characterized by the formation of immune granulomas in involved organs. "Thus, it is plausible to consider a functional mechanism between FCRL1 and cigarette smoking in sarcoidosis." (PMID 31819081, 2019).
Sepsis (1 paper, 2024). Sepsis is defined as life-threatening organ dysfunction caused by a dysregulated host response to infection. "The expression of some of those genes (FCRL1, TNFRSF13C, CD22, CD79A, POU2F2) continue to be upregulated during sepsis recovery stage too." (PMID 38898888, 2024).
type 1 diabetes (1 paper, 2023). "In a genome-wide association analysis of autoantibody positivity in type 1 diabetes (T1D) cases, the authors associated rs4971154 in exon 5 of FCRL1 with islet antigen-2 (IA-2A), one of T1D-associated anti-islet autoantibodies." (PMID 36788507, 2023).
tumor (8 papers, 2013 to 2025). "Taken together, these findings collectively elucidate that FcRL1 orchestrates critical oncogenic programs by not only potentiating tumor cell proliferation but also reinforcing apoptosis resistance." (PMID 40650084, 2025). "Temperature values of melting curve peaks of GPM6B (A), MAGEA12 (B) and FCRL1 (C) amplicons in tumor samples and normal liver tissues in Chinese (Ch) and Bangladeshi (B) cohorts as analyzed by HRM." (PMID 23950870, 2013). "Given the limited efficacy of current therapies for relapsed/refractory DLBCL, targeting FCRL1 could address an unmet clinical need by offering a novel, mechanism-based approach to modulate B-cell signaling and enhance anti-tumor immunity." (PMID 41836520, 2025). "The protein expression of FCRL1, GRIK2, MAPK12, and OR51B5 showed differential level between normal colon tissue and tumor tissue." (PMID 38144182, 2023). "Preliminary research indicates that FCRL1 and BAFF may act synergistically in B-cell malignancies, as their signaling pathways overlap significantly in promoting tumor survival and resistance mechanisms." (PMID 39941037, 2025). "Moreover, we found that IBC tumour-infiltrating B cells also presented high levels of immature signals, which was reflected mainly in the significantly high expression of five molecules, CD22, FCRL1, FCRLA, HVCN1, and SP100, in IBC tumour-infiltrating B cells." (PMID 40624675, 2025).
cancer (2 papers, 2013 to 2022). A tumor composed of atypical neoplastic, often pleomorphic cells that invade other tissues. "The probes correspond to three genes GPM6B, MAGEA12, and FCRL1 that were overexpressed and demethylated in our set of HCC patients and up-regulated in many other types of cancer." (PMID 23950870, 2013). "MAGEA12 was shown before to be repressed in normal cells by promoter methylation and activated in cancer cells by demethylation, whereas the role of GPM6B and FCRL1 methylation in promoter activity was not previously tested." (PMID 23950870, 2013).
blood cancers (1 paper, 2024). "Among the proteins associated with risk of haematological cancers, we identified associations with risk of multiple blood cancers for members of the FC-receptor protein [FCRL1, FCRL2, FCRL3, FCRL5, FCRLB] and TNF receptor families [TNFRSF4, TNFRSF9, TNFRSF13B, TNFRSF13C, TNFSF13B, TNFSF13]." (PMID 38750076, 2024).
kidney (1 paper, 2020). "In the present study, the expression levels FCRL1 gene were assessed using real-time PCR in PBMCs derived from kidney transplant rejected and non-rejection patients and compared with the control group." (PMID 34466580, 2020).
FCRL1 also shares sentences with these, for which no sentence is quoted: breast carcinoma (2 papers); chronic lymphocytic leukemia (2); Graves disease (2); metastatic melanoma (2); non-Hodgkin lymphoma (2); Von Willebrand disease (2); arteritis (1); asthma (1); bladder carcinoma (1); brain tumors (1); colorectal cancer (1); follicular lymphoma (1); infection (1); lung carcinoma (1); lymphoid leukemia (1); multiple myeloma (1); oral squamous cell carcinoma (1); pancreatic cancer (1); prostate carcinoma (1); psoriasis (1); rheumatoid arthritis (1); SeSAME syndrome (1); Takayasu arteritis (1); testicular cancer (1).